CDKN2A (cyclin dependent kinase inhibitor 2A)
Diseases named in the same sentence as CDKN2A in open-access papers (continued):
Sharing a sentence is not in itself a finding about the gene and the disease.
tumor (continued). "The fundamental mechanism might be that loss-of-function mutations of CDKN2A lead to loss of both proteins encoded by it, p14ARF and p16INK4a, releasing G1/S and G2/M cell-cycle checkpoints and resulting in uninhibited cell proliferation and tumor formation." (PMID 36275737, 2022). "Hence, FDX1, DLD, DLAT, and CDKN2A may play important roles in immune interactions and may be associated with tumor immune evasion." (PMID 36531222, 2022). "In addition, CDKN2A, is also designated as a molecular risk factor for tumor progression in NMIBC." (PMID 34885040, 2021). "In addition, CDKN2A expression may contribute to the regulation of tumor-associated macrophages, dendritic cells, and T cells." (PMID 34405225, 2021). "Recent evidence demonstrates that loss of CDKN2A expression in tumor cells correlates with different immunological processes within the tumor that may impair immunological surveillance suggesting that p16 not only regulates cellular homeostasis but also tissue homeostasis." (PMID 33918220, 2021). "A CDKN2A inactivating mutation may lead to activation of cyclin dependent kinases, thus permitting an inappropriate progression through the cell cycle and promoting uncontrolled tumor cell proliferation." (PMID 33704917, 2021). "Similarly, CDKN2A loss in H3.1K27M-bearing cells suggests that this oncohistone requires different secondary mutations to compensate for the loss of Polycomb silencing at tumor suppressor genes." (PMID 32902381, 2020). "Additionally, the status of the cdkn2a locus of an individual tumor might predict its response to Ezh2 loss." (PMID 30080881, 2018). "We next sought to determine whether the AML-like tumour and cellular phenotypes observed in our system are specifically related to the Tsc2 and Cdkn2a loss-of-function genotype or whether any genetic combination that causes transformation and sphere formation would give similar results." (PMID 29133867, 2017). "In the absence of somatic copy number variations or mutations, the fully transformed phenotype of the MNTI may have arisen in infancy because of the combined effects of a germline CDKN2A mutation, tumor promoting somatic fusion genes and epigenetic deregulation." (PMID 27519597, 2016). "Across six domains, four cross-cutting themes with prognostic and potential theranostic value emerged: copy number alterations, particularly CDKN2A/B loss; SWI/SNF complex dysfunction; stroma-tumor ratio; and immune microenvironment heterogeneity." (PMID 42121852, 2026). "Mechanistic studies have found that high doses of CDKN2A can enhance tumor cell migration by activating the Wnt/β-catenin pathway or promoting goblet cell mucus secretion." (PMID 41601652, 2026). "Even though CDKN2A/B does not per se function as a molecular target, there is great potential for enhancing treatment outcomes through the restoration of the tumor-suppressing capabilities of CDKN2A/B." (PMID 41438586, 2026). "Homozygous loss of the 9p21 locus encompassing CDKN2A, CDKN2B, and MTAP is the most frequent copy number alteration across tumor types, making it a promising target for precision medicine strategies." (PMID 42000949, 2026). "Compared with those in normal tissue, KEAP1, STK11, and CDKN2A were highly expressed in the tumor samples of NSCLC patients (P < 0.01)." (PMID 41491583, 2026). "This immunomodulatory effect is closely related to CDKN2A expression levels—high expression allows tumor cells to secrete IL-10, which can induce Treg differentiation, further weakening the anti-tumor immune response." (PMID 41601652, 2026).
tumor (continued). "In independent GEO cohorts, CDKN2A exhibited excellent tumor-normal discrimination in CESC (AUC = 0.982) and moderate discrimination in UCEC (AUC = 0.761)." (PMID 41898813, 2026). "Melanocytic tumorigenesis is deeply influenced by recurrent genetic alterations involving chromosome 9p21, a critical region that harbors key tumor suppressor genes, most notably CDKN2A and MTAP." (PMID 41596618, 2026). "Molecular analysis showed that the tumor tissue, composed solely of rhabdoid cells, also harbored a BRAF V600E mutation and homozygous CDKN2A deletion, molecular signatures of PXA, along with loss of INI1 expression." (PMID 40231261, 2025). "Loss of function mutation in the MTAP gene is caused by homozygous deletion of the 9p21 chromosomal locus that also encompasses the tumor suppressor genes CDKN2A/B." (PMID 41439984, 2025). "While CDKN2A (p16INK4a) is classically recognised as a tumour suppressor that inhibits cyclin‐dependent kinases and induces cell cycle arrest, emerging evidence suggests context‐dependent oncogenic functions in certain cancer types." (PMID 41310877, 2025). "More recently, other molecular biomarkers, such as CDKN2A/B homozygous deletions, have been shown to alter the biology of these low-grade tumours." (PMID 40136387, 2025). "RARB (Retinoic Acid Receptor Beta) plays a critical role in cell differentiation and growth inhibition, while CDKN2A (Cyclin-Dependent Kinase Inhibitor 2A) is a tumor suppressor involved in cell cycle regulation." (PMID 39982247, 2025). "CDKN2A, located on chromosome 9, is a critical tumor suppressor gene that regulates the G1/S phase transition via p16INK4a protein." (PMID 40182139, 2025). "In ASTROs PNC, only one tumour showed a homozygous CDKN2A/B deletion, whilst MYCN amplifications and RB1 alterations were frequently observed." (PMID 39899075, 2025). "The whole-exome sequencing revealed a variety of common oncogenic mutations in the original tumor and HMucBOT-2, including KRAS, ARID1A, ARID1B, and NF1, while CDKN2A remained wild-type." (PMID 40427213, 2025). "Consistent with prior studies investigating metabolic reprogramming in cancer, we observed significant upregulation of key cuproptosis-related genes, including FDX1, GLS, and CDKN2A, in tumor tissues compared to normal counterparts." (PMID 40410601, 2025). "In a subset of cases, deletions in CDKN2A/B have been identified; an alteration that is correlated with more aggressive tumor behavior and poorer prognostic outcomes." (PMID 41346390, 2025). "Like MGMT, the highest percentage of tumor necrosis was observed in CDKN2A gene amplifications, followed by gene deletions and normal status (p = 0.008)." (PMID 40002588, 2025).
tumor (continued). "This method can support future studies aiming to dissect the functional consequences of CDKN2A alterations in various tumor types." (PMID 40649906, 2025). "Collectively, these results suggest that CDKN2A acts as a tumor promoter that facilitates LAUD progression in vitro." (PMID 41341386, 2025). "The genetic alteration of CRGs was explored, and CDKN2A was the most frequently altered gene with alteration rate as high as 17% in 10,953 tumour patients." (PMID 40560740, 2025). "It promotes the proliferation, invasion, and epithelial-mesenchymal transition (EMT) of HCC by catalyzing the trimethylation of histone H3 at lysine 27 (H3K27me3) to silence tumor suppressor genes, such as CDKN2A and PTEN10." (PMID 41298718, 2025). "While CDKN2A/B genes have been established as tumor suppressor genes, the role of MTAP in tumorigenesis has seen contradicting perspectives." (PMID 41439984, 2025). "Consistent with the TCGA data, western blot analysis demonstrated markedly higher CDKN2A protein levels in tumour tissues compared to their normal counterparts, confirming the clinical relevance of CDKN2A overexpression in CRC." (PMID 41310877, 2025). "We next investigated the anti-tumor efficacy of adagrasib and abemaciclib in intracranial tumor models carrying KRAS-G12C and CDKN2A loss." (PMID 40317086, 2025). "Many of these genes, including tumor suppressors such as CDKN2A, HLA-A, and FAT4, have established roles in hematolymphoid malignancies." (PMID 41008837, 2025). "DAPK1 is predicted to interact with CDKN2A, an essential tumor suppressor gene involved in cell cycle regulation and cellular senescence." (PMID 40611883, 2025). "CDKN2A is a gene located in the p21 arm of chromosome 9, which is directly involved in the regulation of the cell cycle, acting as a tumor suppressor." (PMID 41463274, 2025). "In contrast to this, the presence of a CDKN2A/B homozygous deletion prompted 87% of clinicians to classify the tumour as high-grade and pursue adjuvant therapy accordingly." (PMID 40136387, 2025). "Among the six model genes, ASPH, CDKN2A, and NINJ1 exhibited strong correlations with tumor-associated immune cells." (PMID 39980566, 2025). "Activation of specific genes results in the deposition of trimethylated histone H3K27me3 at the CDKN2A promoter, promoting tumor invasiveness." (PMID 40630199, 2025). "Paired comparisons further confirmed the upregulation of FDX1, DLAT, PDHA1, GLS, and CDKN2A in tumor samples." (PMID 40410601, 2025). "According to the classification of central nervous system (CNS) tumors by the WHO, the highest CNS WHO grade, 4, is assigned to astrocytomas with a homozygous deletion of the cell cycle checkpoint CDKN2A/B, tumor necrosis, or microvascular proliferation." (PMID 40849395, 2025). "Recently, we found that concurrent, in vivo Crispr-mediated targeting of the Cdkn2a tumor suppressor locus allows for immortalized cell lines to be efficiently generated." (PMID 41008846, 2025).
tumor (continued). "Other genes, including MYB proto-oncogene like 2 (MYBL2), cyclin dependent kinase inhibitor 2A (CDKN2A), and stathmin 3 (STMN3) were significantly upregulated in tumor tissues from CRC patients and were significantly associated with specific bacterial genera." (PMID 40313460, 2025). "The methylation profiling reclassified the tumour as pleomorphic xanthoastrocytoma, a class further supported by the presence of a homozygous deletion of CDKN2A/B." (PMID 41033792, 2025). "In contrast, both CDKN2A, a gene with tumor suppressive potential in both T-ALL and B-ALL, as well as KRAS, a B-ALL driver gene, were upregulated (Fig. SF5A)." (PMID 41282185, 2025). "The wound healing and transwell assay revealed that silencing CDKN2A significantly impaired the tumor cell migration and invasion." (PMID 39950044, 2025). "As tumor cells migrate deeper into the dermis, they acquire additional alterations, including mutations in genes such as PTEN, NOTCH1, and CDKN2A, that contribute to proliferative advantage, immune evasion, and matrix degradation." (PMID 41463022, 2025). "Its defining characteristics are the presence of tumor necrosis, microvascular proliferation, and/or homozygous deletion of Cyclin-Dependent Kinase Inhibitor 2A/B (CDKN2A/B)." (PMID 41562896, 2025). "Case #3, which displayed hemizygous loss of CDKN2A/MTAP on MIP, demonstrated focal positivity for both p16 and MTAP in less than 25% of the tumor tissue." (PMID 40227557, 2025). "To validate these clinical observations, we examined CDKN2A protein expression in our cohort of paired tumour and adjacent normal tissues." (PMID 41310877, 2025). "In our present study, p16INK4a was undetectable in tumor tissues of CT26 tumor-implanted mice, which can be explained by the fact that the CDKN2A gene that encodes p16INK4a is known to be deleted in a homozygous manner in CT26 cells." (PMID 40806223, 2025). "The cyclin-dependent kinase inhibitor 2A (CDKN2A) gene and the cyclin-dependent kinase inhibitor 2B (CDKN2B) gene are two adjacent tumor suppressor genes that are collectively referred to as the CDKN2A/B." (PMID 40017529, 2025). "It was found that CDKN2A was differentially expressed between tumor tissues and normal tissues, and there was an upregulated trend in PTC, which was verified by qRT-PCR." (PMID 39253931, 2025). "Surprisingly, despite its established role as a tumour suppressor in many contexts, CDKN2A depletion significantly inhibited CRC cell proliferation, as evidenced by CCK‐8 assays." (PMID 41310877, 2025). "On the other hand, we report the somatic mutational landscape of HCC in our cohort, identified exclusively in the tumor tissues, with APC (100%), ALK (94%), HNF1A (56%), CDKN2A and HRAS (50%) emerging as the most frequently mutated genes." (PMID 41567639, 2025). "We analyzed CDKN2A expression across various tissue samples, including normal, adjacent, and tumor tissues, as well as normal intestinal epithelial cells (NCM460) and multiple CRC cell lines (HT29, HCT116, SW620, SW480)." (PMID 39895793, 2025).
tumor (continued). "We established the cell cluster identity using the SingleR tool and confirmed the identified tumor clusters based on the expression of CDKN2A and KRT14 for SCC." (PMID 40597205, 2025). "The MTAP gene is located on chromosome 9p21, near the Cyclin-dependent Kinase Inhibitor 2A (CDKN2A) tumor suppressor gene." (PMID 40157258, 2025). "Loss of p16INK4A function due to CDKN2A mutations or deletions leads to increased CDK4/6 activity, uncontrolled cell cycle progression, and tumor growth." (PMID 40281353, 2025). "The percentage of PTEN and CDKN2A edits in the biopsy samples was nearly 10%, reflecting the presence of other non-tumor cells in the samples, including normal liver tissue adjacent to the tumors and tumor-infiltrating immune cells." (PMID 39780710, 2025). "Our results reveal that CDKN2A is significantly more expressed in tumor tissues compared to normal and adjacent non-tumor tissues." (PMID 39895793, 2025). "As a tumor suppressor gene, CDKN2A negatively regulates the cell cycle and promotes cellular senescence." (PMID 39925808, 2025). "In multiple myeloma, miR-192 acts as a tumor suppressor by targeting IL-17Rs, and bioinformatic analyses suggest it connects with the bone marrow microenvironment by interacting with CDKN2A, influencing tumor progression." (PMID 40087755, 2025). "Immunohistochemistry (IHC) experiment confirmed the higher expression of CDKN2A in THCA samples than para-tumor samples." (PMID 39914044, 2025). "The reverse transcription real-time PCR assay revealed higher expression of tumor markers CDKN2A, EGFR, and PDGFRL in monophasic SS compared to biphasic tumors." (PMID 41155410, 2025). "As sensitivity for detecting copy number alterations across different assays varies, reported CDKN2A/B and aneuploidy results should be interpreted carefully in the context of tumor cellularity and viability." (PMID 39500722, 2025). "In EAC, chronic inflammatory states correlate with sustained methylation of CDKN2A, silencing E-cadherin and promoting epithelial–mesenchymal transition, further reinforcing tumor progression." (PMID 40871387, 2025). "Our findings align with recent studies reporting CDKN2A upregulation in CRC tissues and its association with poor prognosis, supporting the notion that p16INK4a function is highly context‐dependent and can be reprogrammed in specific tumour environments." (PMID 41310877, 2025). "Hypermethylation of CDKN2A suppresses its role in regulating the G1-to-S phase cell cycle transition, enhancing cellular survival and tumor progression." (PMID 40589575, 2025). "Among the key genes affected in DLBCL are MYC, SLIT2, KLF4, and CDKN2A, whose inactivation facilitates uncontrolled proliferation and tumor progression." (PMID 40943058, 2025). "It was found that high-risk patients showed stronger immune escape and worse prognosis, and that genes such as CDKN2A played an important role in tumor cell migration, invasion and apoptosis." (PMID 39950044, 2025). "Oxidative DNA damage further contributes to epigenetic changes in the CDKN2A gene, leading to the downregulation of two key cyclin-dependent kinase tumour suppressors, p16INK4 and p27Kip1." (PMID 41007812, 2025). "circMET functions as a molecular scaffold that physically interacts with YTHDF2, facilitating its recruitment to CDKN2A mRNA and thereby promoting m6A-dependent decay of this tumor suppressor transcript." (PMID 40986143, 2025).